RPL36 (ribosomal protein L36)
Description:
Component of the large ribosomal subunit. The ribosome is a large ribonucleoprotein complex responsible for the synthesis of proteins in the cell. Inhibits C2CD2L/TMEM24-dependent transport of phosphatidylinositol, the precursor of phosphatidylinositol 4,5-bisphosphate (PI(4,5)P2), from its site of synthesis in the endoplasmic reticulum to the cell membrane. This leads to down-regulation of the PI3K-AKT-mTOR signaling pathway.
Synonyms: DKFZp566B023; L36; eL36
Tractability: Small molecule: an approved drug acts on it; a structure with a bound ligand is known; a high-quality ligand is known. PROTAC: ubiquitination databases record sites on it; its protein half-life has been measured; a small molecule that binds it is known. Other modalities: a drug acting on it is in phase 2 or 3 trials.
Target class: Other cytosolic protein
Gene: Protein-coding gene on chromosome 19 (5,674,947 to 5,691,881, forward strand). Ensembl gene ENSG00000130255.
Subcellular location: Cytoplasm, cytosol; Cytoplasm; Endoplasmic reticulum
Subcellular location (Human Protein Atlas): Cytosol
Pathways (Reactome):
Metabolism of proteins: Eukaryotic Translation Termination; Formation of a pool of free 40S subunits; GTP hydrolysis and joining of the 60S ribosomal subunit; L13a-mediated translational silencing of Ceruloplasmin expression; PELO:HBS1L and ABCE1 dissociate a ribosome on a non-stop mRNA; Peptide chain elongation; Ribosome Quality Control (RQC) complex extracts and degrades nascent peptide; SRP-dependent cotranslational protein targeting to membrane; ZNF598 and the Ribosome-associated Quality Trigger (RQT) complex dissociate a ribosome stalled on a no-go mRNA
Metabolism of RNA: Major pathway of rRNA processing in the nucleolus and cytosol; Nonsense Mediated Decay (NMD) enhanced by the Exon Junction Complex (EJC); Nonsense Mediated Decay (NMD) independent of the Exon Junction Complex (EJC)
Cellular responses to stimuli: Response of EIF2AK4 (GCN2) to amino acid deficiency
Developmental Biology: Regulation of expression of SLITs and ROBOs
Disease: Viral mRNA Translation
Metabolism: Selenocysteine synthesis
Genetic constraint (gnomAD): Loss-of-function variants: 0 observed, 6.9 expected, observed/expected ratio (o/e) 0, 90% interval 0 to 0.43. That is too few expected variants to judge how well the gene tolerates losing a copy. Missense variants: 131 observed, 137.06 expected, observed/expected ratio (o/e) 0.96, 90% interval 0.83 to 1.11. Synonymous variants: 74 observed, 52.16 expected, observed/expected ratio (o/e) 1.42, 90% interval 1.17 to 1.72.
Homologues: Orthologues: chimpanzee RPL36 (100% identical), dog RPL36 (100% identical), guinea pig RPL36 (100% identical), macaque RPL36 (100% identical), mouse Rpl36 (100% identical), pig RPL36 (100% identical), rat Rpl36l3 (100% identical), rat AABR07007675.1 (98% identical), tropical clawed frog rpl36 (95% identical), zebrafish rpl36 (92% identical), rat Rpl36l2 (90% identical).
Diseases named in the same sentence as RPL36 in open-access papers:
RPL36 is named in the same sentence as 24 diseases in open-access papers, as found by Europe PMC text mining. Sharing a sentence is not in itself a finding about the gene and the disease. The quoted sentences say what the papers report.
glioma (6 papers, 2018 to 2022). A benign or malignant brain and spinal cord tumor that arises from glial cells (astrocytes, oligodendrocytes, ependymal cells). "Patients were divided into RPL36 high and low expression groups based on mRNA levels, and the association between RPL36 transcript expression in glioma tissues and clinicopathological characteristics was assessed." (PMID 28922548, 2018). "LncRNA PLAC2 inhibits the nuclear translocation of STAT1, thus reducing RPL36 expression, inhibiting glioma cell proliferation, and inducing cell cycle arrest." (PMID 35113786, 2022). "PLAC2 expression was down‐regulated whereas that of RPL36 was up‐regulated in glioma as compared to normal brain tissues." (PMID 28922548, 2018). "Next, we analysed RPL36 mRNA levels by qRT‐PCR in the same 20 additional normal brain and 55 glioma tissue samples and found that RPL36 was up‐regulated in glioma tissues." (PMID 28922548, 2018). "Moreover, Western blot analysis and immunohistochemistry revealed that the protein level of RPL36 in glioma tissues were up‐regulated." (PMID 28922548, 2018). "However, the function and mechanism of action of RPL36 in glioma are unclear." (PMID 28922548, 2018). "Furthermore, RPL36 promotes cell proliferation and G1/S cell cycle progression in glioma." (PMID 30596102, 2018). "Nuclear PLAC2/STAT1 binds to the ribosomal protein L36 (RPL36) promotor to decrease its expression and inhibit proliferation of glioma via cell cycle arrest by downregulating CDK2." (PMID 33050646, 2020). "Our microarray data revealed that STAT1 was up‐regulated in glioma tissues (fold change = 2.193; P < 0.05), whereas a tandem mass spectrum analysis also identified STAT1 as a potential binding partner of RPL36." (PMID 28922548, 2018). "Pearson correlation analysis revealed that there is a negative correlation between PLAC2 and RPL36 mRNA levels in glioma tissues (Spearman r = −0.313, P < 0.05)." (PMID 28922548, 2018).
hepatocellular carcinoma (3 papers, 2017 to 2025). A malignant tumor that arises from hepatocytes. "Related studies suggest that RPL36 may be involved in the early stages of hepatocellular carcinoma, acting as an independent and potentially prognostic indicator for resection of hepatocellular carcinoma, and playing a prognostic role in renal clear cell carcinoma." (PMID 40008552, 2025). "RPL36 was reported as a tumor suppressor to restrain KRAS-induced pancreatic cancer, and was a promising prognostic marker in hepatocellular carcinoma." (PMID 35145966, 2022). "To date, eL36 (rpL36) plays a role in cisplatin resistance in human carcinoma cells, the radiosensitivity in NSCLC (non-small cell lung cancer) cells is regulated by uS3 (rpS3), and eL24 (rpL24) may have effects on drug resistance mechanisms in hepatocellular carcinoma HepG2 cells." (PMID 28273808, 2017).
colon cancer (2 papers, 2018 to 2023). "On the other hand, RPL11 and RPL18 proteins had moderate intensity in colon tissue, whereas RPS15 and RPL36 showed strong staining intensity in colon cancer tissue." (PMID 37888706, 2023). "Further analysis revealed that some of these genes, notably rps15, rpl11, rpl18, and rpl36, are significantly increased in primary adenocarcinoma tissue samples and co-ordinately predict for worse overall survival of colon cancer patients." (PMID 37888706, 2023). "We found that higher expression of RPS15, RPL11, RPL18 and RPL36 could individually predict worse overall survival (OS) of patients with colon cancer compared to the low expression of these genes." (PMID 37888706, 2023). "Finally, based on this evidence, we hypothesized that since these genes are implicated in similar pathways related to ribosomal biosynthesis and protein translation, RPS15, RPL11, RPL18 and RPL36 expression levels may coordinately predict the survival of patients with colon cancer." (PMID 37888706, 2023).
Diamond-Blackfan anemia (2 papers, 2012 to 2021). A congenital aregenerative and often macrocytic anemia with erythroblastopenia. "The most well characterized is Diamond Blackfan anemia (DBA), which results from haploinsufficiencies in several different RP genes (RPS24/eS24, RPS17/eS17, RPL35A/eL33, RPL5/uL18, RPL11/uL5, RPS7/eS7, RPL36/eL36, RPS15/uS19, RPS27A/eS31) and RPS19/eS19, which is mutated in 25% of patients." (PMID 33565275, 2021).
Hyperglycemia (2 papers, 2017 to 2024). An increased concentration of glucose in the blood. "In diabetic mother, ten Hub genes (RPL36, RPS29, RPL8 and so on) are key factors in the increased macrosomia in hyperglycemia." (PMID 38660519, 2024).
rhabdomyosarcoma (2 papers, 2021 to 2023). A rare aggressive malignant mesenchymal neoplasm arising from skeletal muscle. "In the study of rhabdomyosarcoma, it was found that the abundance of eL36 and eL42 (60S ribosomal protein L36 and L42) increases, while the corresponding mRNA decreases." (PMID 33849452, 2021). "Relative to skeletal muscle fibroblasts, several rhabdomyosarcoma cell lines (RH18, RH28, RH36, RH41, RD, and Kym-1) showed higher levels of eL36/RPL36 and eL42/RPL36A, while uL18/RPL5 remained unchanged." (PMID 37047306, 2023). "Additionally, eL36/RPL36 and eL42/RPL36A mRNA levels in rhabdomyosarcoma were less than half of the mRNA level in the skeletal muscle fibroblasts, suggesting strong translational control." (PMID 37047306, 2023).
thyroid cancer (2 papers, 2018 to 2025). "We have shown that pY397 FAK is localized in the nucleolus in aggressive thyroid cancer cells where it interacts with nucleolar proteins involved in ribosomal biogenesis including NOP56, TOP1, RPL36, and PRKDC." (PMID 40458728, 2025).
breast carcinoma (1 paper, 2022). "And two target genes (ULK2 and RPL36) were significantly positively correlated with LRRC75A-AS1 expression in breast cancer." (PMID 35145966, 2022). "Thus, RPL36 might be the most potential inflammation-related target gene of LRRC75A-AS1/miR-3127-5p pathway in breast cancer." (PMID 35145966, 2022). "High expression of RPL36 and RPL27A indicated favorable prognosis in breast cancer." (PMID 35145966, 2022). "Finally, an inflammation-related ceRNA network in breast cancer at the single cell level was established based on lncRNA LRRC75A-AS1, miR-3127-5p, miR-2114-3p, RPL36 and RPL27A mRNAs." (PMID 35145966, 2022). "Finally, the prognostic values of RPL36, RPL27A and TMCC2 in breast cancer were evaluated using Kaplan-Meier plotter database." (PMID 35145966, 2022). "Our analytic results together with these reports indicated that RPL36 and RPL27A might be downstream key targets of LRRC75A-AS1/miR-3127-5p/miR-2114-3p pathways in breast cancer." (PMID 35145966, 2022).
Fabry disease (1 paper, 2023). Fabry disease (FD) is a progressive, inherited, multisystemic lysosomal storage disease characterized by specific neurological, cutaneous, renal, cardiovascular, cochleo-vestibular and cerebrovascular manifestations. "Fabry disease (FD) is a rare genetic condition caused by mutations in the GLA gene, located on the X chromosome in the RPL36-HNRNPH2 readthrough genomic region." (PMID 38155709, 2023).
lymphoma (1 paper, 2013). A malignant (clonal) proliferation of B- lymphocytes or T- lymphocytes which involves the lymph nodes, bone marrow and/or extranodal sites. "The relative mRNA expression levels of 4 ribosomal protein genes that were up-regulated in CUP (RPS7, RPL11, RPS10, and RPL36) were compared with the levels in normal lymphoma and 24 known cancer types." (PMID 23671674, 2013).
cancer (10 papers, 2013 to 2023). A tumor composed of atypical neoplastic, often pleomorphic cells that invade other tissues. "To determine whether any of these mutations affect the properties or function of alt-RPL36, we generated HEK 293T stable cell lines expressing seven cancer-associated alt-RPL36 mutants." (PMID 33479206, 2021). "Taken together, these results suggest that several cancer-associated alt-RPL36 variants exhibit altered expression and phosphorylation, which may affect alt-RPL36 function." (PMID 33479206, 2021). "A number of cancer-associated point mutations in the human RPL36 gene have been previously reported, and we queried whether any of these mutations could alter the sequence of alt-RPL36." (PMID 33479206, 2021). "For example, ribosomal protein L36 contributes to establishing cisplatin resistance in human cancer cells." (PMID 32725721, 2020). "RPL36 has the potential to be applied to the development of ribosomal stress‐based cancer therapeutics." (PMID 28922548, 2018). "It is known that lncRNA PLAC2 inhibits cancer progression by interacting with STAT1 and RPL36." (PMID 35475470, 2022).
tumor (10 papers, 2009 to 2025). "In the C1 cluster (ribosomal small subunit assembly), genes such as RPS27 and RPL36 were significantly upregulated, indicating enhanced protein synthesis in tumor cells, which supports rapid proliferation." (PMID 40463392, 2025). "In contrast genes involved in development and differentiation (Arid5b, Inmt, Grem2, Gdap10), cell metabolism (Alas1, Gsta1, Thrsp, Fdft1, Elovl6), tumor growth (SerpinA4, Cish, Rpl36), and cell cycle control (PLK3, Myc, HNF6/Onecut1) were downregulated." (PMID 33004985, 2020). "PLAC2 suppressed tumour cell proliferation in an RPL36‐dependent manner and induced cell cycle arrest via down‐regulation of CDK2." (PMID 28922548, 2018). "In the present study, we found that overexpression of PLAC2 blocked tumour cell proliferation and cell cycle progression in vitro and tumorigenesis in vivo by decreasing the level of RPL36 via interaction with STAT1." (PMID 28922548, 2018). "Moreover, PLAC2‐overexpressing tumours showed reduced expression of Ki‐67 and RPL36 as detected by immunohistochemistry (P < 0.05)." (PMID 28922548, 2018). "Expression of RPL36 was found to be higher in the early tumor stages (I, II)." (PMID 22709827, 2012).
infection (2 papers, 2021 to 2025). The state of being infected such as from the introduction of a foreign agent such as serum, vaccine, antigenic substance or organism. "Importantly, this interaction was specific as rpS3 did not crosslink to another large ribosomal subunit protein rpL36, and was only captured in ribosomes isolated from VSV-infected cells, consistent with increased rpL40 occupancy during infection." (PMID 41279401, 2025).
RPL36 also shares sentences with these, for which no sentence is quoted: pancreatic cancer (2 papers); adenocarcinoma (1); B-cell lymphoma (1); macrosomia (1); non-small cell lung carcinoma (1); osteosarcoma (1); paraganglioma (1); pheochromocytoma (1); renal clear cell carcinoma (1); thymoma (1); type-2 diabetes (1).